Y_RNA (Y RNA )
Gene: Miscellaneous RNA gene on chromosome 5 (100,021,804 to 100,021,906, forward strand). Ensembl gene ENSG00000199378.
Homologues: Orthologues: chimpanzee Y_RNA (100% identical), macaque Y_RNA (91% identical). Paralogues in human: Y_RNA (87% identical), Y_RNA (86% identical), RNY3 (85% identical), Y_RNA (85% identical), RNY3P1 (84% identical), Y_RNA (84% identical), Y_RNA (83% identical), RNY3P14 (83% identical), RNY3P5 (82% identical), Y_RNA (82% identical), Y_RNA (81% identical), RNY3P11 (80% identical), and 93 more.